MTOR (mechanistic target of rapamycin kinase)
Diseases named in the same sentence as MTOR in open-access papers (continued):
Sharing a sentence is not in itself a finding about the gene and the disease.
cancer (continued). "L‐type amino acid transporter 1 (LAT1) plays a crucial role in amino acid uptake and is linked to cancer cell survival through activation of the mammalian target of rapamycin (mTOR) pathway." (PMID 40923294, 2025). "Mechanistic targets of rapamycin complex (mTOR) which consists of mTOR1 and mTOR2 mutation are involved in most cancer." (PMID 39759114, 2025). "Malfunctions in elements of this pathway, including excessive activity of PI3K, increased activity of AKT, and loss of mTOR function, are well-known contributors to treatment resistance and the advancement of cancer." (PMID 41041347, 2025). "By leveraging the availability of phenotype GWAS data, we performed a MR-phenome-wide association study (PheWAS) to explore possible non-cancer uses of mTOR inhibitors." (PMID 40299431, 2025). "mTOR has also been implicated in various diseases, including cardiovascular disease, cancer, and metabolic disorder." (PMID 40002810, 2025). "These nanoparticles regulate the PI3K/AKT/mTOR pathway to suppress autophagy, hence enhancing the susceptibility of cancer cells to chemotherapy." (PMID 40076496, 2025). "Studies on the TSC/mTOR pathway highlight its critical role in tumor biology, positioning TSC2 as a crucial target for developing precision medicine strategies to treat cancers associated with mTOR dysregulation." (PMID 41181577, 2025). "The discovery that PIK3CA mutations activate the PI3K/AKT/mTOR pathway, which also plays a pivotal role in oncogenesis, has opened the door to repurposing targeted therapies initially developed for cancer." (PMID 40861611, 2025). "IMPDH cytoophidium formation has been linked to rapid cell proliferation and an active PI3K/AKT/mTOR pathway, which are well‐known characteristics of many cancers." (PMID 40186514, 2025). "The PI3K/Akt/mTOR pathway plays a central role in regulating cell proliferation, growth, and survival, and its dysregulation is a hallmark of many cancers." (PMID 41020838, 2025). "In various cancers, mutations in its components or hyperactivation of upstream signals can cause abnormal activation of the mTOR signaling pathway, like in breast cancer, lung cancer, and prostate cancer." (PMID 40673277, 2025). "Cancer: Although the mTOR kinase itself is rarely mutated in cancer, its signaling is frequently disrupted by upstream oncogenic pathways such as PI3K-Akt and Ras-driven MAPK cascades." (PMID 41356921, 2025). "On the other hand, it restricts glycolysis by inhibiting PI3K/AKT/mTOR, implying a dual function of preventing and causing cancer." (PMID 40579785, 2025). "Induces autophagy-associated apoptosis in cancer cells.Inhibits the PI3K/AKT/mTOR pathway by reducing p-PI3K expression.Increases ROS production, leading to AMPK activation, upregulation of ULK1, and phosphorylation of Beclin-1, thereby promoting autophagy." (PMID 41211420, 2025). "MTOR integrates nutrient, energy and growth-factor signals to regulate protein synthesis, metabolism and cell growth, and dysregulation of mTOR signaling has long been implicated in tumorigenesis and cancer progression." (PMID 41300706, 2025). "Dysregulation of the PI3K/AKT/mTOR axis is a hallmark of cancer metabolic reprogramming, contributing to uncontrolled cell growth and survival." (PMID 41281744, 2025). "The PI3K-Akt-mTOR pathway is one of the most frequently altered pathways in cancer, with mutations leading to uncontrolled cell proliferation and survival." (PMID 40851957, 2025). "For example, one study demonstrated that ITGB2 promotes OSCC proliferation by enhancing glycolytic activity in cancer-associated fibroblasts (CAFs) through the PI3K/AKT/mTOR pathway." (PMID 41181127, 2025). "Dysregulation of mTOR signaling has been linked to a range of pathological conditions, including cardiovascular diseases, cancer, and metabolic disorders." (PMID 41373947, 2025). "Abnormal activation of mTOR is particularly associated with uncontrolled cell proliferation and resistance to apoptosis in cancer." (PMID 40445424, 2025).
cancer (continued). "The PI3K/AKT/mTOR pathway promotes the survival and growth of cancer cells when the pathway is activated due to mutations in the PI3K gene or the loss of the PTEN gene." (PMID 41008874, 2025). "Research on the molecular mechanisms underlying the modification of mTOR signaling by nanoparticles is necessary to maintain the targeted therapeutic effect on cancers." (PMID 40717210, 2025). "During radiation treatment, natural medicines interrupt EMT signs and affect pathways such as EGFR, TGF‐β, Notch, Wnt, ERK, mTOR, and NF‐κB, which are associated with increased radioresistance in cancer." (PMID 40895189, 2025). "Rapalogs have been shown to have mixed success in treating a variety of cancers with mTOR mutations." (PMID 40943615, 2025). "In this review, we demonstrate the association between the mTOR pathway and cancers, including CSCs." (PMID 39349424, 2024). "Despite the findings highlighting the mTOR inhibition as a central molecular node in the transition of cancer cells to the latent phenotype, modus operandi of mTOR in the cancer cell dormancy is still regarded as both causal and paradoxical." (PMID 38418814, 2024). "Current knowledge indicates that the dysregulation of mTOR signal is associated closely with cancer occurrence, making mTOR an attractive therapeutic target of cancer (Popova and Jücker, 2021)." (PMID 38533254, 2024). "The polyP levels in humans have been shown to stimulate multiple signaling pathways, including the mTOR pathway, and decreased levels of polyP have been linked to several pathological conditions, such as cancer." (PMID 38993675, 2024). "The results demonstrated that TLS-associated genes were enriched in several cancer and immune-related pathways, such as the mTOR signaling pathway, ECM receptor interaction, and Notch signaling pathway." (PMID 39595209, 2024). "Dysregulation of the mTOR pathway has been implicated in several diseases, including cancer, neurodegenerative disorders, and metabolic disorders." (PMID 38397056, 2024). "Previous studies implicated PI3K/Akt/mTOR signaling pathway in cancer stem cells (CSCs) enrichment and hence chemoresistance." (PMID 39107323, 2024). "SHP2-activating mutation leads to persistent activation of the RAS/ERK and mTOR pathways, which is important for cancer cell proliferation." (PMID 38451719, 2024). "Since PI3K/Akt/mTOR was previously linked to ALDH-1 expression in cancer, signal cascade members were estimated in MDA-MB-231 cells exposed to different treatments." (PMID 39107323, 2024). "Prior research indicated that the SPP1 protein secreted by cancer-associated fibroblasts augmented drug resistance by activating the PI3K/AKT/mTOR signaling pathway through integrin-mediated PKCα phosphorylation." (PMID 39066845, 2024). "These signaling pathways (commonly PI3K/AKT/mTOR signaling) are activated as a result of tumorigenic mutations in the cancer cells." (PMID 38721006, 2024). "Further, combining mammalian target of rapamycin (mTOR) inhibitors with sonic hedgehog inhibitors has been shown preclinically to enhance disease control and increase the susceptibility of cancer stem cells to chemotherapeutic agents." (PMID 39351436, 2024). "Tumor persisters can display a senescence phenotype which is often correlated with an inhibited mTOR pathway, again causing confusion in understanding the functions of mTOR in cancer cell dormancy." (PMID 38418814, 2024). "Overexpression of these proteins is linked to the abnormal PI3K/AKT/mTOR pathway contributing to increased cancer cell proliferation, a common feature in many cancers including BC." (PMID 39558433, 2024). "The dysregulation of mTOR signaling has been associated with multiple types of cancer, including CRC, where it plays a central role in promoting cell growth and proliferation." (PMID 39404412, 2024).
cancer (continued). "Dysregulation of mTOR signaling has also been implicated in many cancers where uncontrolled cell growth and division directly contribute to tumor development and progression." (PMID 38892329, 2024). "Due to the involvement of the mTOR pathway in the regulation of essential processes such as cell cycle, proliferation, growth, survival, protein synthesis and glucose metabolism, mTOR is closely linked to cancer." (PMID 38539200, 2024). "The disturption or upregulation of mTOR pathways will lead to uncontrollable cell division, causing cancer." (PMID 39301125, 2024). "Previous studies have highlighted the critical role of the PI3K/AKT/mTOR pathway in cancer progression, particularly in O. viverrini-associated CCA." (PMID 39850601, 2024). "Dysregulated activation of the PI3K-AKT-mTOR pathway is frequently reported in cancer research, and mTOR is implicated in chemotherapy resistance as well, prompting our exploration of this pathway." (PMID 38473249, 2024). "Activation of the PI3K/AKT/mTOR pathway has been linked to the tumor immune microenvironment and PD-L1 expression, according to reports, implying a novel indication for cancer immunotherapy." (PMID 38966068, 2024). "Mutational change in AKT overactivates it and causes continuous activation of the PI3K/AKT/mTOR pathway contributing to cell proliferation and other cancer cell properties." (PMID 38889771, 2024). "EZH2, the catalytic subunit of PRC2, is often upregulated in cancer, causing the silencing of tumor suppressor genes, DNA damage response genes, and mTOR pathway regulators." (PMID 39048945, 2024). "PI3K inhibition causes cancer cells to increase the activity of mTOR pathway to compensate for loss of PI3K signaling." (PMID 38172946, 2024). "The critical roles of PI3K-Akt-mTOR signaling are foreshadowed by the discovery of mutations in genes encoding key components involved in the pathogenesis of human diseases, such as cancers." (PMID 38616230, 2024). "Disordered activation of the mTOR pathway has been implicated in various diseases, particularly cancers, metabolic disorders, and neurodegenerative diseases." (PMID 39119480, 2024). "Multiple types of cancer exhibit dysregulated mTOR signaling, and this pathway is frequently associated with carcinogenesis and tumor progression." (PMID 38225540, 2024). "Activation of PI3K and its downstream signaling kinases protein kinase B (AKT) and mammalian target of rapamycin (mTOR) has been associated with oncogenesis and the development of resistance to other anti-cancer therapies." (PMID 39437820, 2024). "In this context, the mTOR pathway is crucial in regulating cell growth, proliferation, and survival, but it is often associated with cancer." (PMID 39766256, 2024). "Overactivation of mTOR in cancer was associated with tumor growth, drug resistance, and a poorer prognosis." (PMID 39193327, 2024). "Research has demonstrated that substances such as apigetrin can cause cell cycle arrest and apoptosis through the PI3K/AKT/mTOR pathway, which, in turn, causes a decrease in cancer cell growth and an increase in cell death." (PMID 39199310, 2024). "APA in the 3’-UTR of mRNAs is associated with cancer pathogenesis and various cellular conditions, including mTOR signaling." (PMID 39349823, 2024). "Loss of this inhibitory effect of SIN1-PH on mTOR increases mTORC2 signaling and occurs in cancer patient-derived mutations of SIN1-PH (D412G and R81T), rendering this SIN1 mutant oncogenic." (PMID 38270460, 2024). "The high expression of mTOR has been linked to increased tumor cell proliferation and a more aggressive cancer phenotype." (PMID 39850811, 2024). "Transcriptomic analysis revealed that FAA up-regulated Egl-9 family hypoxia inducible factor 3 (Egln 3) and downregulated several cancer-associated pathways including Hippo, mTOR, and Wnt signaling." (PMID 38613073, 2024).
cancer (continued). "Deficiency of SMYD5 in HCC cancer cells leads to hypersensitivity to mTOR inhibitors, likely due to a compounded inhibitory effect on protein synthesis." (PMID 39103523, 2024). "Usually, MTOR is dysregulated in cancer through upstream events, and only a few reports exist on human cancer-associated mutations in MTOR itself." (PMID 39696035, 2024). "Upregulation of the MAPK and mTOR signaling pathways allows cancer cells to compensate for PI3K loss of function and maintain proliferative potential despite treatment with PI3K inhibitors." (PMID 38172946, 2024). "The deregulated mTOR pathway has been implicated in multiple cancer types, such as breast and renal cancer, and the inhibition of this pathway has shown therapeutic potential." (PMID 38474373, 2024). "Mutations in the PI3K/Akt/mTOR signaling axis are also associated with advanced cancer or metastasis, indicating the potential role of these mutations in cancer cell invasion and migration to distant sites." (PMID 38542151, 2024). "The PI3K–Akt–mTOR pathway has been implicated in enhancing stemness, a trait associated with aggressive cancer manifestations." (PMID 39394200, 2024). "The molecular mechanisms underlying phagosome maturation during cancer cell phagocytosis, as well as its regulation by mTOR signaling to sustain phagocytosis, warrant further exploration." (PMID 39766137, 2024). "Everolimus (RAD001) is an mTORC1 inhibitor that reduces cancer cell proliferation and induces apoptosis by inhibiting mTOR, thereby reversing trastuzumab resistance caused by the overactivation of the PAM pathway due to PTEN loss." (PMID 39769140, 2024). "Mutations in the MTOR gene can result in the persistent hyperactivation of the mTOR signaling pathway, and over 30 mTOR gene mutations have been identified across various cancer types." (PMID 39742278, 2024). "With next-generation sequencing, somatic alterations in genes encoding various members of the PI3K-Akt-mTOR signaling pathway have been frequently identified in cancers of various tissues of origin." (PMID 38616230, 2024). "The PI3K/Akt/mTOR signaling pathway has increasingly been linked to cancer stem cells (CSCs) in a variety of solid tumors, including TNBC, thus conferring chemoresistance and tumor relapse." (PMID 39107323, 2024). "Dysregulation of mTOR signaling has been implicated in various types of cancer, including lung, breast, liver, renal, pancreatic, and prostate cancers." (PMID 39564119, 2024). "We highlighted, in this review, the dysregulation of mTOR signaling and its strong association with several diseases such as metabolic diseases and cancers, as well as its role in life span regulation." (PMID 38892329, 2024). "The attenuation was due to the downregulation of several cancer-associated pathways, including mTOR signaling." (PMID 38892329, 2024). "Disruptions in mTOR signaling, often due to genetic mutations at the level of signal transduction, are prevalent across a spectrum of cancers." (PMID 39595628, 2024). "The PIK3CA gene encodes the alpha isoform of the catalytic subunit of phosphatidylinositol 3-kinase (PI3K) and plays a key role in the activation of the PI3K/AKT/mTOR signaling pathway, which is critical for regulating cancer-associated cellular processes." (PMID 39743996, 2024). "These medications can cause death in cancer cells reliant on mTOR signaling by triggering autophagy." (PMID 39199310, 2024). "mTOR forms two types of protein complex: mTORC1, and mTORC2, which are both implicated in cancer ferroptosis." (PMID 38960924, 2024). "The unbalanced of the PI3K/AKT/mTOR pathway is associated with the development of various malignant tumors." (PMID 38764054, 2024). "Increased angiogenesis is a hallmark of cancer, and mTOR over-activation can drive the initiation and progression of CRC." (PMID 38891994, 2024). "Dysregulation of the mTOR pathway has been implicated in various diseases, including cancer, cardiovascular disease, and diabetes." (PMID 38654380, 2024).
cancer (continued). "Deregulation of mTOR signaling has been implicated in a range of medical conditions, including cancer, aging, neurodegenerative diseases, and muscle-wasting disorders." (PMID 39107687, 2024). "3, Researchers have identified over 30 mutations of mTOR associated with diverse forms of human cancer 33,34." (PMID 38725843, 2024). "The PI3K pathway with its downstream regulators, the serine/threonine kinase AKT and mammalian target of rapamycin (mTOR), has been implicated in the development and progression of many cancers due to its role in mediating cell survival and proliferation." (PMID 38164150, 2024). "Arginine has been extensively studied in different types of cancer, and it seems to be linked to several oncogenic pathways, including the mammalian Target of Rapamycin (mTOR) cascade." (PMID 39595047, 2024). "The inhibition of the MMP-9-BCL-2-dependent AMPK activation pathway by AgNPs leads to the suppression of mTOR activation, hindering the subsequent pathways linked to cancer proliferation." (PMID 38575697, 2024). "The PI3K/Akt/mTOR pathway is an intracellular pathway directly associated with cell proliferation, growth, and cancer." (PMID 39834948, 2024). "The dysregulation of key cancer-associated genes results in mTOR hyperactivation, enhancing the synthesis of pro-oncogenic proteins that directly impact cellular functions such as proliferation, migration, and angiogenesis." (PMID 39056712, 2024). "The CSC-targeting therapy via mTOR inhibition has shown enhanced anti-cancer efficacy, offering hope for addressing existing limitations in cancer treatment, such as drug resistance caused by the active CSCs." (PMID 39349424, 2024). "Various studies have found that various diseases, such as cancer, obesity, type II diabetes, muscle diseases, and neurodegenerative disorders, are associated with abnormal expression or dysfunction of mTOR." (PMID 38421832, 2024). "They observed that immortalized cancer epithelial cells that have hotspot PIK3CA mutation (H1047R or E545K) were sensitive to the MTOR inhibitor, rapamycin, and its analog everolimus." (PMID 39056802, 2024). "The AKT/mTOR pathway is crucial for promoting cell survival, and its activation is associated with resistance to various cancer therapies and poor prognosis." (PMID 38281034, 2024). "Dysregulation of the phosphoinositide 3-kinase/protein kinase B/mammalian target of rapamycin (PI3K/AKT/mTOR) signaling pathway, a consistent feature of malignant tumors, is intricately linked to ROS generation." (PMID 39055885, 2024). "Collectively, these studies provide a novel perspective towards developing a cancer treatment targeting mEAK-7-associated mTOR signaling in NSCLC and other malignancies exhibiting elevated mEAK-7 expression." (PMID 38532930, 2024). "Hypoxic conditions and the aberrant activation of the mTOR/HIF/VEGF pathway can occur in cancer and TSC-associated tumors." (PMID 38846332, 2024). "Many reports have shown that RAS is associated with metabolic changes in various cancer cell types, and mTOR is involved in glucose and amino acid metabolism." (PMID 38809881, 2024). "Since mTOR signaling is strongly linked with CSCs, it is also associated with cancer, which typically originates from CSCs." (PMID 39349424, 2024). "While mutations in mTOR are rare in cancer, this axis is often activated genetically upstream to mTOR to promote uncontrolled growth." (PMID 39013537, 2024). "Under the pharmacologic activation of the transcriptional factor NR2F1, a master regulator of tumor cell dormancy, cancer cells acquire a dormant phenotype associated with the inhibition of cell cycle progression and mTOR signaling." (PMID 38418814, 2024).